SIRPA (signal regulatory protein alpha)
Diseases named in the same sentence as SIRPA in open-access papers (continued):
Sharing a sentence is not in itself a finding about the gene and the disease.
autoimmune disease (8 papers, 2013 to 2023). A disorder resulting from loss of function or tissue destruction of an organ or multiple organs, arising from humoral or cellular immune responses of the individual to their own tissue constituents. "CD47/signal-regulatory protein alpha (SIRPα) is closely related to developing autoimmune diseases by promoting inflammatory response." (PMID 38111586, 2023). "It is known that CD8a-SIRPα+ cDCs mainly induce CD4+ T cell responses, which is an important effector T cell population in autoimmune diseases, whereas CD8a+SIRPα- cDCs has greater ability to induce a CD8+ T cell response." (PMID 34093583, 2021). "Signal regulatory protein alpha (SIRPα), one of the CD47 ligands, is predominantly expressed in myeloid lineage cells such as dendritic cells (DCs) or macrophages, and CD47-SIRPα signaling pathway is implicated in the development of autoimmune diseases." (PMID 34093583, 2021). "As such, SIRPα will allow scientists and clinicians to follow the expansion or contraction of the functional subset during immunotherapy with relevance not only to infections but also cancer and autoimmune diseases." (PMID 30770827, 2019). "The SIRPα - CD47 axis plays an important role in immune cell homeostasis and in leukocyte trafficking in inflammatory and autoimmune disease models." (PMID 35413056, 2022). "The increase in the production of pro-inflammatory cytokines and the reduction of SIRPα and CD206 that we observed in BWF1 macrophages suggests that during autoimmune disease, the phenotype of PMs switches towards a more pro-inflammatory phenotype." (PMID 35211864, 2022).
myelodysplastic syndrome (8 papers, 2020 to 2026). A clonal hematopoietic disorder characterized by dysplasia and ineffective hematopoiesis in one or more of the hematopoietic cell lines. "Preliminary data for the SIRPα-Fc fusion protein IMM01 in combination with Aza showed promising efficacy and tolerability in patients with treatment-naive chronic myelomonocytic leukemia (CMML) and higher-risk myelodysplastic syndrome (HR-MDS)." (PMID 39040441, 2024). "CSF1R inhibitor and anti-CD47 antibodies or anti-SIRPα antibodies have been applied for solid tumors and some hematologic malignancies such as acute myeloid leukemia and myelodysplastic syndrome (MDS)." (PMID 33644032, 2020).
brain tumors (7 papers, 2017 to 2023). "By antagonizing CD47 (which binds to activating signal regulatory protein-alpha (SIRPalpha) on myeloid cells) with a humanized mAb, pre-clinical investigations have demonstrated that macrophages can be unlocked to phagocytize tumor cells in several pediatric brain tumor models." (PMID 29065490, 2017). "Another therapeutic target, which is probably more relevant for pediatric brain tumors with elevated myeloid cell infiltration, is cluster of differentiation 47 (CD47) on tumor cells that binds to signal-regulatory protein alpha (SIRPα) on myeloid cells and inhibits macrophage-induced phagocytosis." (PMID 34830753, 2021).
Burkitt lymphoma (7 papers, 2018 to 2023). A rare form of malignant mature B-cell non-Hodgkin lymphoma. "The ability of mSIRPα.20A to eliminate subcutaneously engrafted Daudi Burkitt’s lymphoma cells in NSG mice (that express the NOD SIRPA allele) was tested in combination with rituximab, analogous to the xenograft model described previously." (PMID 31801627, 2019). "In this assay human peripheral blood-derived macrophages that endogenously express SIRPα are co-incubated with Burkitt’s lymphoma Raji cells (expressing both CD20 and CD47)." (PMID 31801627, 2019). "In Burkitt lymphoma (BL), KWAR23 (an anti-SIRPα antibody) was found to combine with SIRPα at high affinity and consequently increased the TANs-mediated phagocytosis of BL cells." (PMID 34404434, 2021). "A strong synergistic effect between IMM01 (SIRPα-Fc fusion protein) and IMM40H was recorded in Burkitt’s lymphoma Raji and renal carcinoma cell A498 tumor models." (PMID 37849799, 2023). "A strong synergistic effect of IMM01 (SIRPα-Fc fusion protein) and IMM40H was found on Burkitt’s lymphoma Raji and renal carcinoma cell A498 tumor models." (PMID 37849799, 2023). "When the CD47-SIRPα axis was blocked by an anti-human SIRPα antibody, KWAR23, not only macrophages but also neutrophils infiltrated the tumor in a human Burkitt’s lymphoma xenograft." (PMID 35865547, 2022). "The SIRPα knockout M1 macrophages were then subjected to ADCP assays with CFSE-labeled Raji target cells, a cancer cell line derived from a Burkitt lymphoma and expressing CD47 and CD20 on their surface." (PMID 36077152, 2022).
non-small cell lung carcinoma (7 papers, 2014 to 2025). A group of at least three distinct histological types of lung cancer, including non-small cell squamous cell carcinoma, adenocarcinoma, and large cell carcinoma. "Combination treatment with pembrolizumab in non-small cell lung cancer was a notable exception to the improved ORR of selective SIRPα combination therapy (ORR 5.0%, DCR 40.0%)." (PMID 36439116, 2022). "In non-small cell lung cancer (NSCLC), approximately two-thirds of tumor samples exhibit CD47 overexpression, correlating with increased SIRPα on TAMs." (PMID 40079009, 2025).
viral infection (7 papers, 2019 to 2021). "Mice clear JUNV-C1 infection around 14 dpi; thus, we also analyzed that time point to determine if the higher level of virus infection in the SIRPA KO mice persisted at later times." (PMID 34097709, 2021). "A similar decrease in phosphorylation of endogenous SIRPA was seen after Tacaribe virus infection of TRIM2-transfected U2OS cells." (PMID 30726215, 2019). "We next tested whether the cytoplasmic domain was also required for SIRPA inhibition of virus infection." (PMID 34097709, 2021). "Given the broad anti-viral activity of SIRPA, its function could be targeted to reduce virus infection." (PMID 34097709, 2021). "However, we now show that SIRPα is expressed on activated CTL during viral infection." (PMID 30770827, 2019). "SIRPA interaction with CD47 on target cells decreases phagocytosis by about 50%, which is similar to its effect on virus infection." (PMID 34097709, 2021). "Recently, SIRPα was also reported to be selectively expressed on a small subset of T lymphocytes, i.e., exhausted CD8+ memory T cells emerging after chronic viral infection." (PMID 33162986, 2020). "Here the authors show SIRPa is expressed on a subset of CD8+ T cells with higher proliferative and effector activity during the chronic phase of the immune response to viral infection." (PMID 30770827, 2019). "Thus, SIRPA, like IFITM proteins, is likely a modulator of viral infection." (PMID 34097709, 2021).
COVID-19 (6 papers, 2021 to 2026). A disease caused by infection with severe acute respiratory syndrome coronavirus 2. "Therefore, high CD47 and/or SIRPα levels may affect initial virus control resulting in enhanced virus levels, which may eventually lead to the hyperinflammation and immunopathology observed in severe COVID-19." (PMID 34698067, 2021).
renal cell carcinoma (6 papers, 2021 to 2025). "In comparison to CD70 mAb + SIRPα mAb treatment, CD70/SIRPα BsAb had a greater ability to phagocytose CD70-expressing NHL and renal cell carcinomas in vitro, but no apparent differences were observed in vivo." (PMID 35978372, 2022).
Stroke (6 papers, 2014 to 2025). Sudden impairment of blood flow to a part of the brain due to occlusion or rupture of an artery to the brain. "The present review attempts to summarize the role of CD47 and its associated receptor SIRPα (signal regulatory protein α) during the development of neurodegenerative disorders such as Multiple Sclerosis, Stroke, Parkinson’s, Alzheimer and traumatic brain injury among others." (PMID 34203368, 2021). "In the present review, we have highlighted the current evidence regarding the importance of CD47/ SIRPα in pathologies like stroke, Multiple Sclerosis, Alzheimer’s, spinal cord injuries, TBI, and Parkinson’s." (PMID 34203368, 2021). "SHPS-1/SIRPα is expressed by neurons and phagocytic cells and is recognized to be involved in neuroprotection in experimental stroke in mice." (PMID 25038795, 2014). "SP-D is known to bind TLR2 and TLR4, as well as SHPS-1/SIRPα that are all expressed on and linked to induction of TNF in microglia and macrophages and involved in stroke." (PMID 25038795, 2014). "Since microglial-macrophage-produced TNF and SHPS-1/SIRPα are both known to have neuroprotective and pro-regenerative functions, SP-D could potentially have indirect effects on post-stroke neural plasticity." (PMID 25038795, 2014).
colitis (5 papers, 2022 to 2024). Inflammation of the colon. "In SIRPα deficient mice, a reduction in alternative activated (M2) macrophages was found to be associated with impaired wound healing in experimental colitis." (PMID 37893161, 2023). "SIRPα KO mice show impaired wound healing, associated with defective alternative macrophage (M2 macrophage) induction in experimental colitis." (PMID 37893161, 2023). "Analysis of immunofluorescent staining of SIRPα+ dendritic cells in the Hh/anti-IL10R condition, showed similar distribution between the LA and LP in the context of colitis, which mirrors the findings from the cell-loading analysis." (PMID 38570678, 2024). "SKAP2 is capable of bridging and mediating the recruitment of the SIRPα and SHP1/2 complex to TLR4, which leads to the attenuation of an inflammatory response in an experimental colitis mouse model." (PMID 37893161, 2023). "The overall magnitude of enrichment quantified by log(OR) across all populations was lower during colitis, and IL-1βhiCD103+SIRPα+ and RORγt+MHChi ILC3s were no longer significantly enriched." (PMID 38570678, 2024). "This demonstrated that the SIRPα+ dendritic cells, which are significantly enriched in the LA at steady state, are no longer significantly enriched in colitis." (PMID 38570678, 2024).
diabetes (5 papers, 2010 to 2026). "Human islet endocrine cells were found not to have SIRPA mRNA or to display cell surface SIRPα protein, even after exposure to diabetes-associated cytokines." (PMID 37217603, 2023). "It is fair to speculate that diabetes-associated oxidative stress will impact the binding and activity of CD47 and SIRPα checkpoint blockers." (PMID 37217603, 2023). "Additionally, diabetes-associated genes such as RASGRP3, SIRPA, GATM and ESM1 were downregulated." (PMID 33923831, 2021). "Interestingly, NOD mice carry a polymorphism in the Sirpα gene that induces an 18 amino acid variation in the IgV-like domain of the SIRPα protein, as compared to the non-obese diabetes resistant (NOR) strain." (PMID 34603322, 2021).
multiple sclerosis (5 papers, 2016 to 2025). A progressive autoimmune disorder affecting the central nervous system resulting in demyelination. "Skap2- and Sirpα-deficient mice are resistant to experimental autoimmune encephalomyelitis and collagen-induced arthritis, two models for the human diseases multiple sclerosis and rheumatoid arthritis that have integrin-dependent components." (PMID 28374850, 2017).
myeloma (5 papers, 2019 to 2024). "Pre-clinical studies already showed that combining daratumumab and CD47/SIRPα blockade could be a promising therapeutic approach for T-ALL and multiple myeloma." (PMID 36052078, 2022).
neuroblastoma (5 papers, 2021 to 2026). Neuroblastoma (NB) is the most common solid, extracranial childhood tumor. "In this perspective article, we discuss the potential function of the macrophage inhibitory receptor SIRPA in the homeostasis of tumor-associated macrophages in high-risk neuroblastoma." (PMID 38920727, 2024). "Second, what is the underlying mechanism for high expression of an inhibitory receptor on macrophages (i.e., SIRPA) being associated with a better disease outcome in high-risk neuroblastoma?" (PMID 38920727, 2024). "In contrast to CD47 expression, among the six high-risk neuroblastoma tumors examined, SIRPA expression was mainly observed in macrophages." (PMID 38920727, 2024). "In this article, we discuss our perspective on the CD47/SIRPA blockade therapy in high-risk neuroblastoma and the dual role of the inhibitory receptor SIRPA on macrophages." (PMID 38920727, 2024). "We next investigated the expression of SIRPA in high-risk neuroblastoma tissues by immunohistochemical analysis." (PMID 38920727, 2024). "CD47 is expressed on both tumor and stroma cells, whereas SIRPA expression is restricted to macrophages in high-risk neuroblastoma tissues." (PMID 38920727, 2024). "Consistent with this notion, it has been shown recently that the CD47/SIRPA blockade therapy with anti-CD47 antibody in xenograft models of high-risk neuroblastoma requires an additional opsonizing antibody against neuroblastoma, such as anti-GD2 antibody, to be efficacious." (PMID 38920727, 2024). "This was shown by either genetically deleting CD47 molecules from the surface of several neuroblastoma cells or by using a blocking antibody for SIRPα." (PMID 34503071, 2021). "Here, we examined whether an inhibition of CD47-SIRPα axis, by either a genetic disruption or by using an antagonistic agent for SIRPα, allows neutrophils to more efficiently kill dinutuximab-opsonized neuroblastoma cells in vitro." (PMID 34503071, 2021). "Antibody specifically blocking the CD47 receptor of macrophage, known as SIRPα, can restore antibody-dependent phagocytosis toward NB cells and re-establish the anti-neuroblastoma activity." (PMID 35327550, 2022). "In addition, we hypothesize that an effective and less toxic cure for high-risk neuroblastoma should target SIRPA on macrophages and not CD47 on the tumor cells." (PMID 38920727, 2024). "In a variety of neuroblastoma cell lines, knocking down CD47 or blocking SIRPα on neutrophils increased the neutrophil-mediated ADCC induced by dinutuximab (anti-GD2 antibody)." (PMID 35865547, 2022). "In line with our data on CD47 KO neuroblastoma cells, we found the SIRPα blocking agent alone did not induce neutrophil-mediated cytotoxicity of tumor cells unopsonized with dinituximab." (PMID 34503071, 2021). "Altogether, these results suggest that SIRPα blockade therapy may only be applicable and of benefit when the tumor antigen GD2 is present on the surface of neuroblastoma cells in sufficient amounts and hence ADCC can be triggered upon antibody therapy with dinutuximab." (PMID 34503071, 2021).
Arthritis (4 papers, 2024). Inflammation of a joint. "It has been demonstrated that SIRPα mutant mice (lacking the intracellular signaling domain) have a reduced susceptibility to arthritis induced by type-II-collagen, hence indicating that SIRPα contributes to inflammatory tissue destruction." (PMID 39258954, 2024).
bladder cancer (4 papers, 2023 to 2024). "By analyzing changes in angiogenesis through IHC staining, we found that angiogenesis was aggravated after SIRPα-Fc treatment in bladder cancer." (PMID 39335665, 2024). "Compared with the control antibody treatment, SIRPα-Fc treatment led to significant macrophage phagocytosis of bladder cancer cells expressing CD47 (p < 0.01), confirming the in vitro anti-tumor activity of blocking CD47." (PMID 39335665, 2024). "Their data suggest that the correlation between CD47 and SIRPα expression may play a key role in the progression of bladder cancer." (PMID 37373873, 2023). "Thus, we performed in vitro phagocytosis assays to assess whether the phagocytosis of CD47-expressing bladder cancer cells by human macrophages could be restored after CD47 blockade with the SIRPα-Fc fusion protein." (PMID 39335665, 2024).
cervical cancer (4 papers, 2020 to 2025). A primary or metastatic malignant neoplasm involving the cervix. "Taken together, these results suggest that SIRPα-silenced DC vaccination presented potential therapeutic implications against cervical cancer." (PMID 32411788, 2020). "Therefore, it may be concluded that the CD47/SIRPα axis plays a very important functional role in the VES-induced anti-tumour activity on human cervical cancer cells." (PMID 34093795, 2021). "The SIRPα knockdown in DCs results in increased cytokine (TNF-α/IL-12/IL-6) secretion, IFN-γ secretion by T lymphocytes, and in vitro/in vivo tumoricidal activity against cervical cancer." (PMID 32411788, 2020).
Cognitive impairment (4 papers, 2021 to 2026). Abnormal cognition is characterized by deficits in thinking, reasoning, or remembering. "In a mouse model of postoperative cognitive dysfunction, the downregulation of CD47 and SIRPα expression in the hippocampus was associated with increased microglial synaptic pruning, leading to synaptic loss and the exacerbation of cognitive impairment." (PMID 40313098, 2026). "Loss of microglial SIRPα results in increased synaptic loss mediated by microglia engulfment and enhanced cognitive impairment." (PMID 33795678, 2021). "In addition, the efficiency of AAV transduction in microglia is limited, which may affect the result, although we found reduced expression of CD47 and SIRPα and increased synaptic engulfment, synapse loss, and cognitive impairment in PND model." (PMID 35360151, 2022). "During AD pathology, microglial SIRPα signal is disrupted, which subsequently induces excessive elimination of synapses and enhances cognitive impairment." (PMID 33795678, 2021). "Inhibition of microglial SIRPα signal remarkably exacerbates synaptopathology and cognitive impairment by promoting aberrant synaptic elimination in AD mice model." (PMID 33795678, 2021). "Hidden platform test and spatial probe trial results suggested that microglial SIRPα ablation accelerated cognitive impairment in AD mice at 5 months age, even preceding the plaque formation." (PMID 33795678, 2021). "Importantly, the knockout of SIRPα impaired CD47 recognition, thus resulting in exacerbated synaptic pruning and cognitive deficits." (PMID 40313098, 2026). "We tried to find the reason why SIRPα overexpression could not improve the synaptic function and cognitive impairment in PND model." (PMID 35360151, 2022). "SIRPα overexpression could not ameliorate the cognitive impairment in PND mice." (PMID 35360151, 2022). "SIRPα overexpression could not improve the synaptic dysfunction and cognitive impairment in PND." (PMID 35360151, 2022). "Absolutely, cognitive impairment could not be improved by SIRPα overexpression." (PMID 35360151, 2022). "SIRPα overexpression led to decreased PSD95 expression and dendritic spine density, but without worse cognitive impairment, which may also due to complex body regulation and downstream mechanisms of CD47–SIRPα signal." (PMID 35360151, 2022).
endometriosis (4 papers, 2021 to 2023). The growth of functional endometrial tissue in anatomic sites outside the uterine body. "Endometrial CD91+ macrophages overexpressed SIRPα (phagocytosis inhibitor) and CD64 (associated with inflammation) in endometriosis, and they were more abundant in mild versus severe disease." (PMID 35421980, 2022). "Notably, we found that endometrial CD91+ macrophages and CD1a+ dendritic cells overexpress SIRPα—which acts to inhibit efferocytosis by these cells—in women with endometriosis compared to controls." (PMID 35421980, 2022). "We found that macrophages that overexpress SIRPα in endometriosis are CD91+." (PMID 35421980, 2022). "Interestingly, the anti-phagocytosis marker SIRPα (CD172a) was increased on phagocytic CD91+ macrophages and CD1a+ dendritic cells in cases versus controls in the proliferative phase, suggesting decreased phagocytic capacity of these populations in endometriosis patients." (PMID 35421980, 2022). "Notably, we found that endometrial CD1a+ dendritic cells also overexpress SIRPa in women with versus those without endometriosis, indicating that other endometrial phagocytic cells may also be dysregulated in women with endometriosis." (PMID 35421980, 2022).